MIR34BHG (MIR34B and MIR34C host gene)
Synonyms: SPARCLE
Gene: Long non-coding RNA gene on chromosome 11 (111,510,593 to 111,513,892, forward strand). Ensembl gene ENSG00000286028.
Gene Ontology:
Biological process: miRNA-mediated post-transcriptional gene silencing